RPS26 (ribosomal protein S26)
Diseases named in the same sentence as RPS26 in open-access papers:
RPS26 is named in the same sentence as 43 diseases in open-access papers, as found by Europe PMC text mining. Sharing a sentence is not in itself a finding about the gene and the disease. The quoted sentences say what the papers report.
Diamond-Blackfan anemia (17 papers, 2012 to 2025). A congenital aregenerative and often macrocytic anemia with erythroblastopenia. "RPS26 is ubiquitously expressed and is mutated in Diamond-Blackfan anaemia, as well as having a large effect-size eQTL and being linked to numerous traits, including atopic disease." (PMID 41022800, 2025). "For example, the genotypability of genes RPL15 and RPS26 (associated with the bone marrow disorder Diamond-Blackfan anemia – OMIM 615550,613309 –) improved to 100%, from 49.98% and 47.13%, respectively." (PMID 32523024, 2020). "While the precise biological functions of RPS26 remain incompletely understood, many studies have focused on its association with various diseases and its potential as a biomarker, including Diamond-Blackfan anemia (DBA), type 1 diabetes, and fragile X-associated conditions." (PMID 41301418, 2025). "Our experiments suggest that binding of metal ions and protons to specific sites at the Rps26-RNA interface allows for direct sensing of Na+ and H+ concentrations, and implicate Asp33, a residue mutated in Diamond Blackfan Anemia (DBA) in mediating salt-dependent effects." (PMID 35213229, 2022). "In the Diamond-Blackfan Anemia (DBA), ribosomes with deficient ribosomal protein RPS26 preferentially translate mRNAs from stress-response pathway while those having proficient RPS26 recognize mRNAs with defined Kozak sequence." (PMID 35207490, 2022). "The gene RPS26 (Ribosomal protein S26) is a disease-related gene, and the mutation of RPS26 usually causes Diamond-Blackfan Anemia." (PMID 40622919, 2025). "Our data implicate a residue in Rps26 involved in Diamond Blackfan Anemia in mediating the effects of Na+." (PMID 35213229, 2022). "Moreover, mutations in genes encoding RPS26 and TSR2 were associated with hematopoiesis impairment that underlies the genetic blood disorder Diamond-Blackfan anemia (DBA)." (PMID 40377206, 2025). "Notably, ribosomal subunits were either unchanged or decreased, and several genes implicated in Diamond-Blackfan Anemia (TSR2 ribosome maturation factor [TSR2], RPS26, RPS17) clustered in the group showing the largest decreases in translation efficiency." (PMID 33137094, 2020). "In humans, mutations in RPs have been implicated in hematopoetic disorders, most notably Diamond-Blackfan anemia (DBA), which has been attributed to mutations in RPS19, RPS26, RPS24, RPS17, RPS10, RPS7, RPL35a, RPL26, RPL11, and RPL5." (PMID 23382688, 2013). "The patient tested negative for pathogenic variants in genes associated with Diamond-Blackfan anemia: RPS19, RPL5, RPL11, RPS26, RPL35a, and RPL15." (PMID 35774100, 2022).
type 1 diabetes (10 papers, 2011 to 2024). "The locus 12q13 (lead SNP rs11171739), previously identified as a type 1 diabetes locus, was associated with a pattern including two cis eQTLs, RPS26 and SUOX, and 5 trans eQTLs, one of which (MADCAM1) is a potential candidate for mediating T1D susceptibility." (PMID 22144904, 2011). "Cis-acting regulation of RPS26 expression was reported previously in the context of type 1 diabetes and verified in a large monocyte dataset but the biological significance is unclear." (PMID 38421405, 2024). "In other words, the SNPs with the highest effects on type 1 diabetes would tend to also have the highest effects on RPS26 expression, and the direction of effects would be consistent." (PMID 32477401, 2020). "These include ATP13A1 with BMI, ERAP2 for both inflammatory bowel disease and celiac disease, RPS26 for both type 1 diabetes and rheumatoid arthritis, and BTN2A1 with schizophrenia." (PMID 30061686, 2018). "The trans-eSNPs showing mediation by GATA2 (3q21.3), FCN1 (9q34.3), and RPS26 (12q13.2) are also associated with white blood cell subtypes, systemic inflammation (and FCN1 protein activity), and type 1 diabetes risk, respectively." (PMID 25474530, 2014). "Notably, this variant is in high LD with rs11171739 (r2 = 0.86 in CEU) previously implicated in blood cell cis association with RPS26 and SUOX and trans association with several targets, as well GWAS associations for Type I diabetes." (PMID 24973796, 2014).
anemia (3 papers, 2019 to 2025). A reduction in the number of red blood cells, the amount of hemoglobin, and/or the volume of packed red blood cells. "RPS26 has been positively correlated with anemia, which is a common complication in patients with IBD, and identified as a differentially expressed gene marker of IBD." (PMID 40728886, 2025).
anorexia nervosa (3 papers, 2018 to 2025). A disorder most often seen in adolescent females characterized by a refusal to maintain a minimally normal body weight, an intense fear of gaining weight, a disturbance in body image, and, in postmenarcheal females, the development of amenorrhea. "Rps26: Rps26, a component of the ribosomal machinery, has been implicated in altered protein synthesis in neuropsychiatric disorders, including anorexia nervosa." (PMID 40656047, 2025). "While these genes that respond to fasting are not enriched in the anorexia nervosa associated gene sets, we highlight RPS26 and DLALRD3, which are proximal to common variants associated with anorexia nervosa." (PMID 32651428, 2020). "While our results cannot be directly compared to past transcriptomic studies of cases and controls, we also mark RPS26 and DALRD3 as key genes in anorexia nervosa." (PMID 32651428, 2020).
autoimmune disease (3 papers, 2017 to 2023). A disorder resulting from loss of function or tissue destruction of an organ or multiple organs, arising from humoral or cellular immune responses of the individual to their own tissue constituents. "One co-eQTL SNP, rs1131017, that is associated with several autoimmune diseases, affects the co-expression of RPS26 with other ribosomal genes." (PMID 37072791, 2023). "These co-eQTLs shed light on the biological processes upstream of individual cis-eQTLs, such as that seen for rs1131017, which affects RPS26 expression levels and is associated to autoimmune diseases." (PMID 37072791, 2023). "There were several studies that implicated RPS26 in autoimmune diseases as a possible factor that can evoke autoimmunity." (PMID 31598692, 2019). "Interestingly, specifically in T cells, the SNP additionally affects co-expression of RPS26 and a group of genes associated with T cell activation and autoimmune disease." (PMID 37072791, 2023). "Here we show cell type-specific regulation of transcript levels of genes associated with several autoimmune diseases in CD4+ and CD8+ T cells including a trans-acting regulatory locus at chr12q13.2 containing the rs1131017 SNP in the RPS26 gene." (PMID 28248954, 2017).
diabetes (3 papers, 2012 to 2025). "In summary, our study identified significant genetic correlations between obesity and microvascular complications in diabetes, successfully pinpointing shared risk SNPs and genes—most notably, RPS26, which showed the strongest genetic association." (PMID 40245477, 2025). "Ribosomal and translational machinery components, such as RPS26, RPS26L1, and EEF1G, highlight potential shifts in protein synthesis capacity or cellular homeostasis that accompany preclinical diabetes." (PMID 40740938, 2025).
psoriasis (3 papers, 2013 to 2024). An autoimmune condition characterized by red, well-delineated plaques with silvery scales that are usually on the extensor surfaces and scalp. "Another study mapped eQTLs in skin tissues from psoriasis patients and looked at overlap with psoriasis GWAS results, finding significant enrichment of psoriasis GWAS SNPs in their eQTL dataset, with effects on the expression of genes such as FUT2, RPS26 and ERAP2." (PMID 32778885, 2020).
asthma (2 papers, 2021 to 2023). "In addition, the RPS26 gene was found to be significant in both European and Japanese asthma-GWASs." (PMID 37875944, 2023). "After applying the Bonferroni correction (Psmr < 2.08 × 10–6) and HEIDI threshold (PHEIDI > 0.01), a total of four SMR genes were identified: three SMR genes (AHI, MED24, and DDX5) with the European asthma-GWAS summary and one SMR gene (RPS26) with the Japanese asthma-GWAS summary." (PMID 37875944, 2023).
COVID-19 (2 papers, 2023 to 2025). A disease caused by infection with severe acute respiratory syndrome coronavirus 2. "Previous studies have also shown that RPS26 is associated with SARS-CoV-2 that persists in COVID-19 patients, and RPS26 is in turn a marker gene that determines the severity of COVID-19 infection in both T and B cells." (PMID 40337271, 2025). "In addition, in 2022, a study found differential expression of RPS26 after COVID-19 mRNA vaccination, demonstrating the validity of RPS26 as a parameter." (PMID 36936955, 2023).
depression (2 papers, 2018 to 2025). "Collectively, these genes contribute to diverse regulatory pathways, including neurotransmitter metabolism (Tph2), neurotrophic signaling (BDNF), metabolic regulation (Sucnr1), and ribosomal function (Rps26), supporting their multilayered regulatory roles in the development of depression." (PMID 40656047, 2025).
lymphoma (2 papers, 2022 to 2023). A malignant (clonal) proliferation of B- lymphocytes or T- lymphocytes which involves the lymph nodes, bone marrow and/or extranodal sites. "Besides lymphoma, raised free levels of several RPs (RPS15A, RPL23A, RPS26 and RPS29) have been associated with aggressiveness and bad prognosis also in other malignancies." (PMID 36226068, 2022).
myelodysplastic syndrome (2 papers, 2020 to 2022). A clonal hematopoietic disorder characterized by dysplasia and ineffective hematopoiesis in one or more of the hematopoietic cell lines. "In particular, it is interesting to note that among the most prevalent DBA genes, RPS26 is the only one that has never been found mutated in patients that developed cancer or myelodysplastic syndrome." (PMID 36579335, 2022). "These distinctive properties of Rps26 may give rise to some of the phenotypic characteristics observed in DBA patients with RPS26 mutations, specifically, the fact that no RPS26-mutated patient has developed myelodysplastic syndrome or cancer, so far." (PMID 36579335, 2022).
premature ovarian failure (2 papers, 2018 to 2025). "Among the downregulated transcripts and proteins, premature ovarian failure (POF) markers such as Rps26, Figla, Gdf9, Aire and Fmrp1 were detected, so the absence of CDK12 clearly resembles a POF phenotype." (PMID 40148269, 2025).
rheumatoid arthritis (2 papers, 2018 to 2023). A chronic, systemic autoimmune disorder characterized by inflammation in the synovial membranes and articular surfaces. "Despite the great interest in this locus and the role of RPS26 in lymphocytes, the associated pathways and biological processes that underlie the rheumatoid arthritis GWAS signal are still largely unknown." (PMID 37072791, 2023). "We confirmed overlap with risk regions in T1D and rheumatoid arthritis using SMR analysis which found the RPS26 endometrial cis-eQTL expression levels were associated with risk SNPs for T1D and rheumatoid arthritis, the gene passing both the SMR and HEIDI test suggesting a causal relationship." (PMID 30061686, 2018).
appendicitis (1 paper, 2016). Acute inflammation of the vermiform appendix. "Conversely, most of the coding transcripts, such as RPLP1 and RPS26, were decreased in the blood of appendicitis patients." (PMID 27417541, 2016).
campomelic dysplasia (1 paper, 2021). "In this respect, it is tempting to speculate on the classification of campomelic dysplasia (OMIM #114290), as links between Sox9 and genes involved in ribosomopathies were identified in the present work (SBDS, Rpl11, and Rps26)." (PMID 34235151, 2021).
hay fever (1 paper, 2023). "Interestingly, several studies have highlighted a connection of RPS26 with T cell activation and survival, and the associated co-eQTL SNP rs1131017 is associated with the enriched immune-mediated diseases (RA, CD, MS, hay fever)." (PMID 37072791, 2023).
IgA nephropathy (1 paper, 2021). "Compared with the mesangial of donor, the gene CLIC1 and RPS26 were up‐regulated in mesangial of IgA nephropathy(IgAN), whereas the gene JUNB was up‐regulated in podocyte of IgAN in comparison with that of donor." (PMID 33754492, 2021).
influenza (1 paper, 2021). An acute viral infection of the respiratory tract, occurring in isolated cases, in epidemics, or in pandemics; it is caused by serologically different strains of viruses (influenzaviruses) designated A, B, and C, has a 3-day incubation period, and usually lasts for 3 to 10 days. "RPS26 and RPL3 are ribosomal proteins (RP) and both are related to influenza viral RNA transcription and replication." (PMID 35186014, 2021).
myopia (1 paper, 2018). "Moreover, it points out that multiple associated ribosomal deficits might play a role in DBA-related phenotypes, considering the simultaneous deletion of three of them in the index case (RPS26, PA2G4 and RPL41), and it confirms the association among SLC39A5 functional disruption and severe myopia." (PMID 30524470, 2018).
neuroblastoma (1 paper, 2025). Neuroblastoma (NB) is the most common solid, extracranial childhood tumor. "(D) A western blot analysis of FMR99xG normalized to Vinculin from the human neuroblastoma cell line (SH-SY5Y) upon silencing of either RPS26 or RPS25." (PMID 40377206, 2025).
Obesity (1 paper, 2025). Accumulation of substantial excess body fat.
polycystic ovary syndrome (1 paper, 2018). A disorder that manifests as multiple cysts on the ovaries. "Here, we studied a susceptibility gene of polycystic ovary syndrome (PCOS), RPS26, which is a ribosomal protein-encoding gene that is highly expressed in the ovary, but the functions of which remain unknown." (PMID 30451825, 2018).
viral infection (1 paper, 2025). "Pathway-based differential co-expression test of this coExQTL indicated rs7305461 disrupted the relationship between RPS26 expression and GRNs involving protein secretion, cellular response to starvation, and response to viral infection." (PMID 41022800, 2025).
vitiligo (1 paper, 2014). Generalized well circumscribed patches of leukoderma that are generally distributed over symmetric body locations and is due to autoimmune destruction of melanocytes. "The same variant also showed strong cis associations with RPS26, and to a lesser degree, SUOX, and was associated with vitiligo." (PMID 24973796, 2014).
cancer (7 papers, 2021 to 2026). A tumor composed of atypical neoplastic, often pleomorphic cells that invade other tissues. "The discovery of genes such as MCM6 and RPS26, which are involved in these interactions, not only underscores the genetic susceptibility to microbiome‐related cancer pathways but also opens up possibilities for targeted therapies." (PMID 39906083, 2025). "The confirmation of a less cancer prone genotype, RPS26-mutated, would influence any cancer screening or surveillance program for individuals with DBA." (PMID 35052397, 2021). "Thus, the hypothesis that patients with RPS26-mutated DBA are less prone to develop cancer than patients with other RP mutations could be related to ribosome heterogeneity for RPS26." (PMID 35052397, 2021). "If these RPS26-deficient 40S subunits would then selectively translate subsets of mRNAs, it seems reasonable to hypothesize that some of these mRNAs may have a protective role in reducing cancer incidence in individuals with DBA haploinsufficient for RPS26." (PMID 35052397, 2021). "In addition to transcription factors, in AML samples, we identified the upregulation of genes that were reported to accelerate leukaemogenesis, including S100A8, S100A9, and RPS26, and the downregulation of genes related to cancer control and defence, such as XIST, GIMAP7, NKG7, and GNLY." (PMID 37615858, 2024). "In contrast, AML1 exhibited higher expression levels of genes encoding ribosomal proteins, including RPS26 and RPS4Y1, which may promote cancer metastasis and spread, and their presence is correlated with increased disease aggressiveness and poor clinical outcomes." (PMID 37615858, 2024). "While the numbers are too small to attach statistical significance to this finding, in the context of the near absence of RPS26 haploinsufficiency in human cancers, the suggested absence of RPS26 haploinsufficiency in DBA-associated cancer is worthy of investigation." (PMID 35052397, 2021). "Nonetheless, we find a subset of genes such as CRYBB2, RPS26, XRRA1, FAM118A,andC2ORF74, all of which show predictive gains of >50% from SNPs in multiple cancers and tumour-adjacent tissue." (PMID 40041206, 2025). "In the setting of the near absence of RPS26 in human cancers, including those in the DBA patient cohort, it is worth noting some of the properties of RPS26 that set it apart from many of the other cancer-associated ribosomal proteins." (PMID 35052397, 2021).
immune disease (2 papers, 2023 to 2025). "However, increased expression of FCRL3, SKAP2, and AP003774 was associated with lower risk of T1D and RA, while decreased expression of BACH2 and RPS26 increased immune disease risk." (PMID 41361473, 2025).
kidney disease (1 paper, 2021). "Little is known about the function of RPS26 in kidney disease." (PMID 33754492, 2021).
RPS26 also shares sentences with these, for which no sentence is quoted: infection (2 papers); acute lymphoblastic leukemia (1); Autoimmunity (1); bone marrow disorder (1); celiac disease (1); colon cancer (1); inflammatory bowel disease (1); Klippel-Feil syndrome (1); metabolic disorders (1); orofacial clefting (1); progressive supranuclear palsy (1); schizophrenia (1); systemic lupus erythematosus (1); tumour (1); ulcerative colitis (1).